PACSIN1 (protein kinase C and casein kinase substrate in neurons 1)
Description:
Plays a role in the reorganization of the microtubule cytoskeleton via its interaction with MAPT; this decreases microtubule stability and inhibits MAPT-induced microtubule polymerization. Plays a role in cellular transport processes by recruiting DNM1, DNM2 and DNM3 to membranes. Plays a role in the reorganization of the actin cytoskeleton and in neuron morphogenesis via its interaction with COBL and WASL, and by recruiting COBL to the cell cortex. Plays a role in the regulation of neurite formation, neurite branching and the regulation of neurite length. Required for normal synaptic vesicle endocytosis; this process retrieves previously released neurotransmitters to accommodate multiple cycles of neurotransmission. Required for normal excitatory and inhibitory synaptic transmission (By similarity). Binds to membranes via its F-BAR domain and mediates membrane tubulation.
Synonyms: SDPI
Tractability: Small molecule: it has a binding pocket of medium quality. Antibody: UniProt places it where antibodies can reach, with medium confidence; its Gene Ontology location is reachable by antibodies, with medium confidence. PROTAC: its protein half-life has been measured.
Gene: Protein-coding gene on chromosome 6 (34,466,061 to 34,535,229, forward strand). Ensembl gene ENSG00000124507.
Subcellular location: Cytoplasm; Cell projection; Synapse, synaptosome; Cell projection, ruffle membrane; Membrane; Cytoplasmic vesicle membrane; Synapse; Cytoplasm, cytosol; Cell membrane
Subcellular location (Human Protein Atlas): Nucleoplasm; Vesicles; Nucleoli
Pathways (Reactome):
Vesicle-mediated transport: Clathrin-mediated endocytosis
Gene Ontology:
Molecular function: phospholipid binding; protein binding; cytoskeletal protein binding; identical protein binding; lipid binding
Biological process: plasma membrane tubulation; cytoskeleton organization; neuron projection morphogenesis; positive regulation of dendrite development; protein localization to membrane; protein localization to plasma membrane; regulation of endocytosis; synaptic vesicle endocytosis; actin filament organization; neuron development
Cellular component: cytoplasm; axon terminus; endosome; perinuclear region of cytoplasm; plasma membrane; ruffle membrane; synapse; COPI-coated vesicle; cytoplasmic vesicle membrane; cytosol; membrane; photoreceptor ribbon synapse; presynaptic endocytic zone
Genetic constraint (gnomAD): Loss-of-function variants: 14 observed, 51.51 expected, observed/expected ratio (o/e) 0.27, 90% interval 0.18 to 0.43. The upper end of that interval is the gene's LOEUF score, 0.43, which puts it in group 1 of 6, group 1 being the genes least tolerant of losing a copy. Missense variants: 416 observed, 550.43 expected, observed/expected ratio (o/e) 0.76, 90% interval 0.7 to 0.82. Synonymous variants: 207 observed, 210.67 expected, observed/expected ratio (o/e) 0.98, 90% interval 0.88 to 1.1.
Homologues: Orthologues: chimpanzee PACSIN1 (100% identical), macaque PACSIN1 (99% identical), guinea pig PACSIN1 (97% identical), rabbit PACSIN1 (97% identical), mouse Pacsin1 (95% identical), rat Pacsin1 (94% identical), pig PACSIN1 (80% identical), dog PACSIN1 (79% identical), zebrafish pacsin1b (75% identical), tropical clawed frog pacsin1 (73% identical), zebrafish pacsin1a (72% identical), Drosophila melanogaster Synd (45% identical), and 1 more. Paralogues in human: PACSIN2 (68% identical), PACSIN3 (50% identical).